PROS1 (protein S)
Diseases named in the same sentence as PROS1 in open-access papers (continued):
Sharing a sentence is not in itself a finding about the gene and the disease.
glioma (continued). "Thus, the inhibition of PROS1 may represent a potential novel strategy to block macrophages to M2 phenotype polarization, and suppress glioma progression." (PMID 36685506, 2022). "We further investigated whether PROS1 regulated the malignant phenotype of glioma." (PMID 36685506, 2022). "Among these pathways, many immune-related pathways were highly associated with PROS1, including CD22 mediated by regulation,immunoregulatory-Internation, chemokine receptors bind chemokines, disease of the immune system, chemokine signaling pathway, IL-18 signaling pathway in glioma." (PMID 36685506, 2022). "However, the study of underlying role and mechanism of PROS1 in gliomas, especially in low-grade gliomas, is almost absent." (PMID 35879775, 2022). "Besides, PROS1 could be a possible biomarker and potential immunotherapeutic target through promoting the glioma immunosuppressive microenvironment and inducing tumor-associated macrophages M2 polarization." (PMID 36685506, 2022). "Using the TIMER online tool, increased PROS1 was observed to be significantly correlated with infiltrations of immune cells, including negatively associated with pDC, NK, and CD56 bright cells, and positively related with macrophages, and neutrophils in glioma." (PMID 36685506, 2022). "Moreover, our research also reveals the mechanism of PROS1 to promote the malignant progress by shaping the immune-suppressive tumor microenvironment, such as T cell failure, immunosuppressive cell infiltration, and M1 macrophages to the polarization of type M2 macrophages in glioma." (PMID 36685506, 2022). "Thus, these part results showed that PROS1 could a possible prognostic marker for glioma patients." (PMID 36685506, 2022). "It is found that the expression of PROS1 had positive correlations with PD-1, PD-L1, PDCD1LG2, CTLA4, HAVCR2, and GZMB (all P <0.05) in glioma." (PMID 36685506, 2022). "Similar results were acquired using data from the GEPIA, TIMER dataset, and CGGA datasets, increased PROS1 was correlated with poor DFS and OS in glioma." (PMID 36685506, 2022). "Besides, from two glioma studies of the GEO database (GSE22866, GSE42656), it’s found that PROS1 expression was significantly increased in glioma tissues than in normal tissues." (PMID 36685506, 2022). "PROS1 mRNA expression was significantly upregulated in all 30 tumour samples compared to that in adjacent normal samples, as well as in 3 glioma cell lines (T98G, U87, and U251) compared to that in the non-malignant human astrocyte cell line NHA." (PMID 35879775, 2022). "It is found that levels of PROS1 expression were negatively correlated with the infiltration of pDCs, NK CD56 Bright cells and positively correlated with Macrophages and neutrophils in glioma." (PMID 36685506, 2022). "Subsequently, we displayed subgroup analyses of prognosis, which indicated that elevated PROS1 expression was correlated with poor overall survival in glioma patients with PR &CR,1p/19q non-codel, astrocytoma, and WHO G2&G3 grade." (PMID 36685506, 2022). "We observed that the IRSs of PROS1, P2RY8, PLAU, CHI3L2, MSR1, CCR5, and TRIM38 were higher than its corresponding IRSs in low-grade glioma, while the IRSs of HAMP, CARD16, and S100A8 in high-grade glioma were lower than low-grade glioma." (PMID 34954691, 2021). "Additionally, six targets are regulated by our miRNAs both in glioma and meningioma: CR2, KNG1, PROS1, F9, MBL2 and F11, while different miRNAs are dysregulated in each cancer type." (PMID 32545233, 2020). "Furthermore, the expression levels of several genes (PLOD3, SLC20A1, ADAM9, FBLIM1, SPOCD1, P4HB, PROS1 and SELENON) were positively correlated with glioma grades." (PMID 32091665, 2020). "However, recent evidence has shown that Pros1 does bind to and activate AXL in glioma sphere cultures 113, and it modulates AXL expression in oral squamous cell carcinoma cell lines 114, suggesting that Pros1 induces receptor activity function differently in different tumor microenvironments." (PMID 32802188, 2020).
glioma (continued). "The results showed that TRIM38, CCR5, PLAU, P2RY8, and PROS1 have a higher immunoreaction score (IRS) in tumors than normal tissues (p < 0.05), while the IRS of HAMP and S100A9 in gliomas were lower than normal tissues (p < 0.05)." (PMID 34954691, 2021). "In addition, PROS1 was found significantly increased in WHO IV, IDH-wildtype, and 1p/19q no-codeletion glioma patients in the CGGA cohort (id mRNA-seq_325)." (PMID 36685506, 2022).
melanoma (34 papers, 2007 to 2026). A malignant, usually aggressive tumor composed of atypical, neoplastic melanocytes. "Here, we show that BAP1 loss leads to increased expression of PROS1 in uveal melanocytes and melanoma cells, which in turn leads to phosphorylation and activation of the receptor tyrosine kinase MERTK on adjacent macrophages, driving them into a suppressive M2-polarized state." (PMID 35954340, 2022). "Of note, MERhigh melanoma cells secreted more PROS1 and PROS1 treatment induced larger colonies in the young mouse lung." (PMID 36646673, 2023). "With the TAM ligands, ProS1 was found to be expressed highly in 786-0 kidney cancer cells and in one melanoma cell line." (PMID 31766614, 2019). "Similarly, we studied if addition of increasing Pros1 concentrations would impact the cytotoxicity of expanded TILs against an autologous melanoma cell line." (PMID 33801886, 2021). "To answer this question of how MerTK inhibition may affect MerTK+ T cells in an antitumor cell response, we studied MerTK signaling in melanoma TILs by examining the impact of Pros1." (PMID 33801886, 2021). "Expression of Tnf, Il1b, Pros1, and Gas6 was enhanced upon tumor growth in vivo, as was Dkk1, in contrast to studies showing down-regulation of DKK genes in melanoma cell lines in vitro, relative to melanocytes." (PMID 37043573, 2023). "This study identified a subtype enriched in advanced melanoma exhibiting a highly differentiated state and possesses immunoregulatory functions, which is predicted to simultaneously send dual signals via the MHC-II and PROS1 pathways, coordinating both the immune and neural microenvironments." (PMID 41383633, 2025).
antithrombin deficiency (32 papers, 2009 to 2025). "Inherited risks include factor V Leiden, activated protein C resistance, prothrombin G20210A, protein S insufficiency, and antithrombin deficiency." (PMID 40943985, 2025). "Protein S or protein C deficiency, activated protein C resistance, and antithrombin deficiency are considered risk factors for CVT." (PMID 40923133, 2025). "We found protein S deficiency, protein C deficiency, anticardiolipin antibodies, lupus anticoagulant, acquired activated protein C resistance, and antithrombin deficiency." (PMID 38025202, 2023). "The major genetic trombophilias as prothrombotic conditions include the following: factor V Leiden (FVL) pathologic variant; G20210 A prothrombin gene pathologic variant;; hyperhomocysteinemia; antithrombin deficiency; and protein C or protein S deficiencies." (PMID 35629384, 2022). "Elevated serum transaminases observed in the majority of our CDG patients were associated with the presence of coagulation disorders, including protein C, protein S, and antithrombin deficiency." (PMID 34291020, 2021). "Testing for protein C, protein S, and antithrombin deficiency is indicated two to four weeks after completion of anticoagulation therapy." (PMID 31309014, 2019). "Inherited thrombophilic factors (factor II and factor V mutation, protein C/protein S/antithrombin deficiency) were available for 168 pregnancies and abnormalities were found in 16 patients (9.5%)." (PMID 29867924, 2018). "The odds ratio for stillbirth for individual defects were antithrombin deficiency of 5.2, protein C of 2.3, protein S deficiency of 3.3, and Factor V Leiden 2.0." (PMID 24455235, 2013). "Hereditary prothrombotic states of clinical importance include factor V Leiden; prothrombin mutation; protein C, protein S and antithrombin deficiency; sickle cell disease; and hyperhomocysteinemia." (PMID 20184700, 2009). "Antithrombin deficiency (levels lower than 72% in infants and 90% in children aged more than 1 year) were reported in 15% (7/46) of cases, protein C deficiencies in 13% (6/46) of cases, and protein S defects (one homozygote) in 9% (4/46)." (PMID 35402350, 2022). "Protein S, protein C and antithrombin deficiency are the major DVT risk factors in Japanese." (PMID 36292507, 2022). "The most common defect was antithrombin deficiency found in 20 (10.9%) patients followed by Factor V Leiden in 9 (5%) (1 had homozygous state and 8 had heterozygous state), protein C deficiency in 6 (3.2%), protein S deficiency in 5 (2.7%), and prothrombin gene mutation in 5 (2.7%) cases." (PMID 34733330, 2021). "The role of the other thrombophilias is less clear; the meta-analysis by Rey and colleagues found that protein C and antithrombin deficiency were not linked with fetal loss, whereas protein S deficiency was associated with late term fetal loss." (PMID 24455235, 2013). "A high risk for arterial thrombosis conferred by protein S or protein C but not antithrombin deficiency was also reported earlier." (PMID 21254740, 2010). "In addition, some pro-thrombotic conditions such as protein C, protein S, antithrombin deficiency have not been investigated in our patients." (PMID 33375456, 2020). "The lack of association between protein S, protein C, or antithrombin deficiency and risk for arterial thromboses in these studies could be explained by the low prevalence of these hereditary deficiencies in the general population." (PMID 21254740, 2010). "In addition, it could be speculated that protein S, protein C, or antithrombin deficiency in these studies might have been acquired rather than hereditary, considering that acquired deficiencies are more prevalent." (PMID 21254740, 2010).
hyperhomocysteinemia (30 papers, 2006 to 2025). A serious metabolic condition caused by mutations in the MTHFR gene, medications, or nutritional deficiency. "In some TAO afflicted patients, the presence of antiphospholipid antibodies and coagulation abnormalities, such as hyperhomocysteinemia, protein S and protein C deficiencies, has been identified." (PMID 33125568, 2020). "We identify hypertension, hereditary protein S deficiency, hypercholesteremia and hyperhomocysteinemia as contributing etiologies in this case." (PMID 30755166, 2019). "We didn’t find an increased incidence of adverse pregnancy outcomes in subjects with protein S deficiency, hyperhomocysteinemia, C677T or A1298C MTHFR homozygous mutation, G20210A Prothrombin homozygous mutation, G1691A factor V homozygous mutation, PAI-1 homozygous mutation." (PMID 23675040, 2007). "Other thrombophilias incude deficiencies in antithrombin III (AT III), protein S, protein C, resistance to the activated protein C (APCR) and elevated homocysteinemia." (PMID 23675040, 2007). "Thrombophilia testing was performed; prothrombin time, partial thromboplastin time, bleeding time, fibrinogen, antithrombin III protein C, protein S, activated protein C (APC) resistance, homocysteinemia, and testing for mutations in the prothrombin and factor V were all normal." (PMID 38978838, 2024). "Thrombophilic abnormalities, either inherited (antithrombin, protein C, or protein S deficiency, with mutations in the FVL, FII, or MTHFR genes) or acquired (antiphospholipid antibodies) should be investigated in patients with CVT, as well as those with hyperhomocysteinemia." (PMID 25221687, 2014).
lung carcinoma (28 papers, 2014 to 2025). "Elevated levels of PROS1 have also been observed in certain cancers, including lung cancer, where PROS1-mediated signaling enhances tumor cell proliferation, migration, and angiogenesis." (PMID 39535659, 2025).
prostate carcinoma (25 papers, 2008 to 2025). A carcinoma that arises from epithelial cells of the prostate gland. "This protein can provide valuable insight for personalised treatment regimens, as high levels of protein S have been found to cause resistance to treatment which stimulates prostate cancer cells through cAMP or IL‐6‐inducing agents." (PMID 39410867, 2024). "The earlier study found that PROS1 expression was significantly higher in prostate cancer and which played a critical role in the progression of prostate cancer." (PMID 36685506, 2022). "Until now, protein S expression has been studied in oral squamous cell carcinoma and prostate cancer, and galectin-1 expression has been identified in renal clear cell carcinoma." (PMID 33453410, 2021). "In recent years, PROS1 has been proven to be a potential target in several cancers, such as breast cancer, bladder cancer, oral squamous cell carcinoma, and aggressive prostate cancer." (PMID 36685506, 2022). "In addition, PROS1 was found to affect prostate cancer cell proliferation and resistance via regulating apoptosis." (PMID 36685506, 2022). "Similar to our findings, Protein S has been shown to induce migration in prostate cancer cells." (PMID 27486820, 2016). "PROS1 expression has been reported to be elevated in aggressive prostate cancer tissue and thyroid cancer tissue, suggesting it may have a role in cancer etiology or progression." (PMID 24810602, 2014).
lupus (24 papers, 2007 to 2026). "This protein S assay can be affected by the presence of lupus anti-coagulant or a specific factor V inhibitor, but we did not identify either of these humoral factors." (PMID 21605440, 2011). "It has been attributed to inhibition of prekallikrein by the lupus anticoagulant or, as recently postulated, to interference with the activation of the protein C and protein S anti-coagulant pathways." (PMID 22121422, 2011). "The correlation of decreased protein S levels with lupus disease activity is consistent with a role for the TAM receptors in scavenging apoptotic cells and controlling inflammation." (PMID 20637106, 2010). "To test whether human systemic lupus erythematosus (SLE) patients might have deficient levels of TAM ligands, we measured Gas 6 and protein S levels in SLE." (PMID 20637106, 2010). "Administration of hCG in lupus-prone mice enhanced reactivity toward several cellular moieties, including known autoantigens; antibodies directed against Protein S, Protein C, and β2-glycoprotein 1, as well as various phospholipids, were significantly enhanced." (PMID 30574119, 2018). "Additionally, this study did not determine the effect of DOACs on true-positive Lupus anticoagulant patients, patients with antithrombin, protein C, or protein S deficiency nor did it evaluate the effect of DOAC-remove®." (PMID 39534247, 2024). "Increased levels of sAxl and sTyro3 have also been found in lupus patient blood, and all three soluble TAMRs can compete for the TAMR ligands Gas6 and protein S to block Mer function." (PMID 24650765, 2014). "Acquired fluctuations in protein S levels may arise from factors such as vitamin K antagonist (VKA) use, chronic infection, severe hepatic disease, systemic lupus erythematosus (SLE), myeloproliferative disorders, renal syndromes, disseminated intravascular coagulation, and oral contraceptive use." (PMID 41393758, 2025). "The patient did not exhibit abnormalities in the protein S and C antigen levels and activity or in lupus anticoagulants, which indicated an inherited thrombophilic predisposition or elevated antiphospholipid antibodies; this suggested an acquired thrombophilic predisposition." (PMID 38975374, 2024).
Sepsis (24 papers, 2012 to 2026). Sepsis is defined as life-threatening organ dysfunction caused by a dysregulated host response to infection. "The profile of MYL9 associated gene interactions for adult sepsis is quite different than that for pediatric sepsis, with association instead with platelet membrane glycoproteins GP5 and GP6, PLOD2, COL6A3, and PROS1." (PMID 32318053, 2020). "NE and epinephrine infusion reduced plasma protein C levels in sepsis patients and NE can downregulate protein S expression in cultured endothelial cells, an effect which is mediated by α1AR, but not by β2AR or α2AR." (PMID 27379911, 2016). "Neonatal PF may result from homozygous or compound heterozygous deficiencies in natural anticoagulants, such as protein C, protein S, or antithrombin III, or secondary to sepsis." (PMID 41869195, 2026). "The expression of PROS1 shows a positive correlation with neutrophil count, activity, and oxidative burst, suggesting its potential as a therapeutic target for conditions like decompensated liver cirrhosis and sepsis." (PMID 38613800, 2024). "PROS1 expression is positively correlated with neutrophil count and activity and oxidative burst, and is a potential therapeutic target for decompensated cirrhosis and sepsis." (PMID 36855207, 2023). "In contrast, there was marked consumption of the natural coagulation inhibitors antithrombin, protein C, and protein S. These results go some way towards explaining why the therapeutic use of recombinant TFPI fails to correct sepsis-associated coagulopathy." (PMID 26377606, 2016). "Accordingly, SPE B-mediated protein S cleavage is speculated to be involved in the pathogenesis of GAS-caused tissue damage, sepsis, and even death." (PMID 27181595, 2016). "However, few downregulated proteins in sepsis patients compared to HC were AHSG, and PROS1, whereas compared to w/o sepsis, patients were AHSG, PROS1, DEFA1, SERPINA3, MPO, and MMRN1 (Azurophil granule, azurophil granule lumen and secretory granule lumen (GO:0042582, GO:0035578 and GO:0034774))." (PMID 35681439, 2022). "Additionally, coagulation factor abundance was predictive of coagulopathic activities that occurred during ST sepsis; e.g., increased fibrinogen as well as increased protein S, FII, FV, FVII, and FXI activities, coupled with diminished levels of AT-III, FX, and FXII activities." (PMID 35349828, 2022). "Similarly, PROS1, the gene encoding protein S, an important regulator of the clotting cascade, was also up-regulated in human renal epithelial cells co-incubated with iMS1 cells, suggesting a possible involvement of MS1 cells in sepsis-related coagulopathy." (PMID 34103408, 2021). "Examples include increased fibrinogen as well as increased protein S, FII, FV, FVII, and FXI activities, coupled with diminished levels of AT-III, FX, and FXII activities during ST sepsis." (PMID 35349828, 2022). "We conclude that the faulty functionality of neutrophils may be due to the autophagy proteins, i.e., DNAJC13, AHSG, TMSB4X, PROS1, and SERPINA3, which can be used as therapeutic targets in decompensated cirrhosis patients with sepsis." (PMID 35681439, 2022). "Proteomic analysis revealed that faulty functionality of neutrophils may be due to the autophagy proteins i.e., DNAJC13, AHSG, TMSB4X, PROS1 and SERPINA3, which can be used as therapeutic targets in decompensated cirrhosis patients with sepsis." (PMID 35681439, 2022). "Earlier studies found deficiencies of the 3 main natural anticoagulants, antithrombin, protein C, and protein S. However, none of these inhibitors block tissue factor, the prime trigger of coagulation during sepsis that is controlled specifically by the tissue factor pathway inhibitor (TFPI)." (PMID 26377606, 2016).